ADAM17 (ADAM metallopeptidase domain 17)
Diseases named in the same sentence as ADAM17 in open-access papers (continued):
Sharing a sentence is not in itself a finding about the gene and the disease.
tumor (continued). "Since its discovery, ADAM17 has been implicated in the initiation and progression of practically all tumor entities, such as colon cancer, breast cancer, lung cancer and gastric cancer." (PMID 34224305, 2021). "Overexpression or increased activation of ADAM17 in tumor cells has been associated with the initiation and progression of carcinomas, especially when EGFR is activated." (PMID 34771725, 2021). "In parallel, miRNA-dependent down-regulation of ADAM9, ADAM10 and ADAM17 was associated with reduced tumor progression, inhibition of cell proliferation and invasion and chemotherapy sensitization of HCC cells." (PMID 33805340, 2021). "Recent evidence has revealed that enhanced ADAM17 expression on the tumor cell surface is associated with tumorigenesis, invasiveness, metastasis, and drug resistance in various cancers." (PMID 34208863, 2021). "A disintegrin and metalloproteinase 17 (ADAM17) is associated with shedding of several substrates involved in tumor progression and known to be expressed by platelets of healthy donors and patients with solid tumors." (PMID 34208863, 2021). "Clinicopathological data analysis showed that ADAM17 level is positively associated with aggressive tumor characteristics." (PMID 32610677, 2020). "Overexpression or enhanced activation of ADAM17 in tumor cells has been linked to cancer initiation and progression, mostly via EGFR activation." (PMID 29662625, 2018). "Considering the importance of ADAM-17 in tumor progression and predicting patient outcomes, we explored the underlying mechanisms of ADAM-17 upregulation." (PMID 29776401, 2018). "ADAM17 catalyzes many critical events associated with tumor invasion and metastasis, including shedding or release of some of the most important protein ligands from transmembrane proteins, and activation of Notch receptor." (PMID 30627328, 2018). "Excess ADAM17 activity leads to an increased release of EGFR ligands, which can drive tumour progression, whilst low ADAM17 activity can cause problems in development and regeneration due to decreased EGFR signalling." (PMID 27731361, 2016). "The results presented here also demonstrate that ADAM17 regulates the expression of key inflammatory mediators, including pro- inflammatory cytokines and Cox-2, in tumor associated macrophages." (PMID 27738494, 2016). "Loss of ADAM17 in macrophages led to reduced Cox-2 expression in response to tumor cell conditioned media." (PMID 27738494, 2016). "In recent years, studies found the high expression of ADAM17 in a variety of human tumors, it reflected the degree of malignancy, promoted tumor invasion and metastasis process, it was associated with prognosis of cancer in patients." (PMID 25351873, 2015). "We postulate that the interaction of ADAM17 with CD13 and its downregulation following CD13 engagement has important implications in AML for the known roles of ADAM17 in tumour-associated cell growth, migration and invasion." (PMID 25246708, 2014). "ADAM17 is involved in the cleavage of numerous surface molecules, most of which are considered to be relevant in tumour-associated processes such as cell growth, migration and invasion (TNF-α, CD44, L1-CAM, L-selectin, ICAM1, CX3CL1, etc.)." (PMID 25246708, 2014). "PAK2, which is known to promotes malignant tumor progression, increased ADAM17/10-Paxillin association and secretion through microvesicles by site-specific phosphorylation." (PMID 26082068, 2012). "ADAM17 further plays a pivotal role in inflammation and cancer, as ADAM17-mediated shedding events have been implicated in regulating inflammatory responses and promoting tumor growth, invasion, and metastasis." (PMID 40143211, 2025). "Collectively, ADAM17 deficiency favors the anti-tumor activity of CD8+ T cells." (PMID 38918390, 2024). "Furthermore, we found that high tumor NOX1 mRNA expression was associated with WT KRAS while both low ADAM17 and MCAM mRNA expression was associated with mutated KRAS." (PMID 38137406, 2023).
tumor (continued). "This raises the possibility that several gain-of-function mutations in the FGFR2 gene could contribute to tumor growth and the formation of metastasis in EC by regulating ADAM17-mediated MAPK signaling pathways." (PMID 37759450, 2023). "Furthermore, 5-FU is also a known activator of ADAM17, the sheddase which causes the shedding of B7-H6 from the tumour cell surface." (PMID 35364779, 2023). "Our investigation revealed that the tumor-driver potential of gain-of-function mutant FGFR2 depends on ADAM17-mediated MAPK activation, while the overexpression of loss-of-function FGFR2 mutants showed only minimal tumorigenicity in the absence of other driver alterations in cell-based assays." (PMID 37759450, 2023). "Evidence suggests that ADAM17 promotes tumor-associated macrophage polarization and angiotensin II-mediated pro-growth and pro-migration signals by shedding EGFR ligands, including heparin-binding EGF-like growth factor (HB-EGF) and AREG (members of the EGF family), from the cell membrane." (PMID 36466812, 2022). "ADAM17 has been implicated in immune regulation of tumor development." (PMID 36466812, 2022). "Interestingly, ADAM17 was also associated with immune cell infiltration and immunomodulators in tumor and paired normal tissues." (PMID 36558177, 2022). "ADAM17 was associated with the increased soluble PD-L1 from tumor cells." (PMID 34182543, 2021). "Higher ADAM17 expression was associated with the metastasis and advanced tumor stage of NSCLC." (PMID 32976115, 2020). "The loss of these other functions may serve to promote inflammation or tumor growth, and in this way neutralize any anti-inflammatory or anti-tumorigenic effects caused by reduced ADAM17 and ErbB signaling." (PMID 29312533, 2017). "To further examine the effects of ADAM17 deletion on inflammatory mediators, we assessed expression levels of Cox-2, which is a downstream target of pro-inflammatory mediators and a key regulator of tumor associated macrophage function." (PMID 27738494, 2016). "Further studies were performed to determine whether ADAM17 is expressed on tumor-associated leukocytes by co-staining tumors for ADAM17 and CD45." (PMID 27738494, 2016). "Analysis of downstream effects of ADAM17 loss in macrophages demonstrates that ADAM17 regulates expression levels of the inflammatory mediator Cox-2, which has been previously shown to regulate tumor associated macrophage function." (PMID 27738494, 2016). "We therefore looked for a TF that could regulate ADAM17 expression in PTEN-deficient tumour cells independently of the PI3K/AKT pathway." (PMID 27941799, 2016). "Tumor associated antigens (TAA) could fulfill this role as ADAM17-mediated shedding of TAA might result in weaker recognition of tumor cells by the immune system." (PMID 23251384, 2012). "Our findings that EC‐linked mutations in FGFR2 increase ADAM17 activity provides a well‐defined description of a molecular mechanism associated with these pathogenic mutations, implicates increased ADAM17 activity in tumour formation and identifies a new druggable target in EC." (PMID 37165578, 2023). "In addition, compared to NSG mice harboring control A549 xenografts, serum levels of human (i.e., tumor‐derived) sIL‐6R, along with cellular staining for pADAM17 and pERK1/2 within tumors, were substantially reduced in mice with ADAM17‐deficient A549 tumor xenografts." (PMID 30833304, 2019). "ADAM17 is reported to have a direct functional role in controlling proliferation and/or migration of cells derived from many tumour types, and it has been implicated in controlling endothelial cell migration and pathological angiogenesis, which is also relevant to tumour growth." (PMID 22792380, 2012). "ADAM17 is implicated in the pathogenesis of colorectal cancer (CRC), with its elevated expression correlating with tumor progression, including deeper invasion, lymph node metastasis, and distant metastasis." (PMID 41050403, 2025).
tumor (continued). "In a previous study, we analyzed the concentration of ADAM10 and ADAM17 in the tumor tissue and surgical margin in patients with CRC and the role of these proteins in other diseases dependent on the inflammatory process, such as DMT2 or CVD." (PMID 39940871, 2025). "Since its discovery, ADAM17 has been increasingly recognized as a key regulator in the tumor microenvironment." (PMID 41050403, 2025). "Hypothetically, the concentration of ADAM 10 and ADAM17 in serum will change later than it will in the tumor or surgical margin tissue." (PMID 39940871, 2025). "Extensive literature has established ADAM17 as a pivotal pro‐angiogenic factor in tumor progression." (PMID 41058008, 2025). "ADAM17-dependent shedding of L-selectin plays a significant role in controlling T cell–dependent immunity to tumours as well as to viruses." (PMID 40651613, 2025). "The function of ADAM17 is not limited to the fields of tumor and immunity; it also plays a role in the development and maintenance of the nervous system." (PMID 41050403, 2025). "In KRasG12D-driven LAC, genetic disruption or inhibition of ADAM17 significantly reduces tumour growth by impairing cell proliferation." (PMID 40427200, 2025). "More recently, molecules important to tumor immunosurveillance have been found to be substrates for ADAM17, and research on the shedding events that this enzyme orchestrates has produced new theories of resistance to common cancer treatments." (PMID 41342182, 2025). "Elevated circAHNAK in ccRCC cells promotes angiogenesis‐related phenotypes in HUVECs by stabilizing ADAM17, a metalloprotease known to facilitate tumor angiogenesis." (PMID 41058008, 2025). "The aim of the study was to assess NLR and PLR and their relationship with selected clinical parameters in CRC patients, as well as the correlation between ADAM10 and ADAM17 in tumor tissue and matched surgical margins with NLR and PLR values." (PMID 39940871, 2025). "qRT‐PCR analysis of ccRCC tumor tissues revealed a strong positive correlation between circAHNAK and ADAM17 expression, as well as between ERβ and ADAM17." (PMID 41058008, 2025). "In the current study, a positive correlation was shown between both ADAM10 and ADAM17 concentrations in the tumor tissue and the surgical margin." (PMID 39940871, 2025). "Tumor-derived EVs (e.g., miR-25-3p, ADAM17, and miR-27b-3p) promote lung PMN vascularization by targeting ECs 92-94." (PMID 40521189, 2025). "The resulting loss of FMR1 disrupts m6A‐dependent recognition and decay of ADAM17 mRNA, leading to ADAM17 accumulation and enhanced tumor angiogenesis." (PMID 41058008, 2025). "Correlations between ADAM10 and ADAM17 concentrations in the tumor tissue and surgical margin, as well as NLR and PLR values, were also examined." (PMID 39940871, 2025). "Treatment with the selective ERβ antagonist PHTPP or the ADAM17 inhibitor JG26 significantly inhibited tumor growth, with combined treatment showing synergistic efficacy." (PMID 41058008, 2025). "The analysis of ADAM10 and ADAM17 concentrations in the tumor tissue and surgical margin in CRC patients and their analysis, depending on selected parameters, were presented in our previous study." (PMID 39940871, 2025). "Secreted via exosomes, elevated ADAM17 enhances endothelial cell angiogenic activity within the tumor microenvironment." (PMID 41058008, 2025). "ADAM17 (TACE) is a membrane‐bound metalloprotease that promotes angiogenesis via multiple mechanisms within the tumor microenvironment." (PMID 41058008, 2025). "Published data show that several ADAMs, including ADAM8, ADAM9, ADAM10, ADAM12, and ADAM17, are overexpressed in tumours." (PMID 40427200, 2025). "Another study showed that the concentrations of ADAM10 and ADAM17 in the tumor tissue and surgical margin of CRC patients differ." (PMID 39940871, 2025).
tumor (continued). "In the tumor microenvironment, ADAM17 promotes the occurrence, development, invasion, and metastasis of tumors by remodeling the extracellular matrix (ECM) and affecting the migration of immune cells." (PMID 41050403, 2025). "Gallic acid exhibits anti-tumor effects on brain gliomas by inhibiting the expression of ADAM17, p-AKT, and p-ERK, thereby suppressing the PI3K/Akt and Ras/MAPK signaling pathways to mitigate tumor cell aggressiveness." (PMID 39045282, 2024). "Consistent with ADAM17 KO mice, CAR-T cells with ADAM17 inhibition displayed increased CD122 expression in both tumor and draining LNs, as well as STAT5 phosphorylation after IL-2 stimulation ex vivo." (PMID 38918390, 2024). "This suggests that both ADAM10 and ADAM17 play crucial roles in regulating the PD-L1/PD-1 pathway which in turn impacts anti-tumor immunity." (PMID 38317965, 2024). "By activating EGFR signaling, but also by shedding RTKs on the cell surface, ADAM17 plays a crucial role in mediating intracellular signal transduction and promotes tumor proliferation, migration and metastasis." (PMID 39506058, 2024). "The ADAM17-dependent pathways are known to be crucial in tumor development and progression and in the modulation of many pathological and physiological processes." (PMID 39768182, 2024). "Although several different ADAMs have been implicated in cancer initiation and progression, as well as conferring resistance to specific cancer therapies in various tumour types, ADAM17 and ADAM10 remain as the two most important metalloproteases." (PMID 38600326, 2024). "The results showed that mice with T cell-specific knockout ADAM17 had remarkably diminished tumor growth and prolonged mouse survival rate compared to WT control mice." (PMID 38918390, 2024). "This is exclusively mediated by CD16A, a low affinity IgG FcR that undergoes rapid shedding from the cell surface by ADAM17 under various conditions, including cryopreservation, activation, proliferation, and by ADAM17 induction in the tumor microenvironment." (PMID 39100677, 2024). "Particularly, the organoid system, regarded as the closest representation of primary tumours, exhibited reliably the combinatorial effect of ADAM17 inhibition and cisplatin in all three individual donors." (PMID 39286024, 2024). "Collectively, we found that ADAM17 deletion can markedly improve the anti-tumor activity of both CD8+ TCR-T and CAR-T cells by enhancing CD122 signaling, highlighting its potential for developing next-generation cancer immunotherapies." (PMID 38918390, 2024). "This indicates that the iRhom2-ADAM17 complex is a potential tumour marker for OSCC, which seems to be in line with the fact that patients with TOC mutations, which increase ADAM17 activity, have a higher risk of developing OSCC." (PMID 38409522, 2024). "Our findings reveal a critical post-translational regulation in CD8+ T cells, providing a potential therapeutic strategy of targeting ADAM17 for effective anti-tumor immunity." (PMID 38918390, 2024). "The summary of signaling pathway shows that ADAM17 activation is associated with many signaling pathways, such as inflammation response (e.g. IL-6, IL-1β, TNF, and TGF-β1), migration of tumor cells, tissue wound, and extracellular matrix organization." (PMID 38341954, 2024). "To better understand the tumor-control advantage of CAR-T cells inhibiting ADAM17, we assessed the proportions and phenotypes of these tumor-infiltrating CAR-T cells 7 days after adoptive transfer." (PMID 38918390, 2024). "This is consistent with literature that ADAM17 mediates the cleavage of CD44 extracellular domain (ectodomain) in various types of cells including tumor cells." (PMID 38177179, 2024). "Inhibition of ADAM17 induced sensitization of tumor cells to cisplatin-induced apoptosis, which was accompanied by a significant reduction in cell viability." (PMID 39506058, 2024). "A role of iRhom1 and ADAM17 in oncogenesis and tumor progression has been well documented in BC15,45." (PMID 38177179, 2024).
tumor (continued). "As expected, CAR-T cells engineered to knock down ADAM17 displayed superior tumor eradication efficacy with increased pro-inflammatory cytokine production and surface CD122 expression." (PMID 38918390, 2024). "Similar results were also seen in WT and ADAM17 KO CD8+ TILs from the direct tumor model, as well as in KLRG1+CD127- CD8+ SLECs from the in vivo acute infection model." (PMID 38918390, 2024). "Preliminary results indicated that exosomal ADAM17 promotes the initial stage of CRC metastasis by cleaving E-cadherin in tumor cells." (PMID 38413999, 2024). "Inhibition of ADAM17 improved the anti-tumor effects of chimeric antigen receptor (CAR) T cells in solid tumor." (PMID 38918390, 2024). "Overall, these findings suggest that CRC-derived exosomal ADAM17 promotes hematogenous tumor metastasis by regulating blood vessel permeability." (PMID 38413999, 2024). "In agreement with the previous results in the direct tumor model, ADAM17 ablation in CD8+ T cells exhibited a robust anti-tumor activity." (PMID 38918390, 2024). "Intrigued by the role of ADAM17 in modulating the anti-tumor reactivity of CD8+ T cells, we next explored the application of inhibiting ADAM17 in CAR-T cell therapy." (PMID 38918390, 2024). "Overall, our study revealed that CRC-derived exosomal ADAM17 effectively blocks VE-cadherin-mediated adhesion to vascular endothelial cells, thereby increasing endothelial barrier permeability and enhancing tumor cell metastasis." (PMID 38413999, 2024). "Complementary gene-silencing experiments were conducted with Caco-2 tumor cells that express high constitutive levels of Xkr8 and ADAM17 substrates." (PMID 37623781, 2023). "First, we analysed the correlation between ADAM17 levels and immune cell infiltration using the Tumour Immune Estimation Resource (TIMER) database." (PMID 38069391, 2023). "The results showed that the expression of ADAM17 was significantly stronger in HCC tissue compared to those in non-tumour tissues." (PMID 38069391, 2023). "In this study, we found that GBM tumor cells released LRIG3 to a soluble form through the regulation of ADAM17 and attenuate the tilt towards an M2-dominant TAM population, thus remodelling the tumor microenvironment and suppressing tumor growth." (PMID 36639372, 2023). "Correlation analyses revealed that ADAM17 was negatively correlated with the purity of the tumour, but positively correlated with the levels of six immune cells, including B cells, CD8+ T cells, CD4+ cells, macrophages, neutrophils, and dendritic cells." (PMID 38069391, 2023). "ADAM17 promotes tumor growth by activating growth factors from the EGF family, as well as by affecting angiogenesis and the secretion of cytokines such as IL-6, IL-10, IL-12 or TNF alpha." (PMID 37185715, 2023). "Multiple studies have shown that ADAM17 participates in the immune regulation of tumours and plays an important role in their formation and development." (PMID 38069391, 2023). "These in vivo data provide further evidence that ADAM17 silencing can sensitize tumor cells to TMZ, which is consistent with the in vitro findings." (PMID 37175410, 2023). "The growth curve of xenografts showed that after ADAM17 knockdown, the transplanted tumor cells were more sensitive to TMZ, and the difference was statistically significant on day 19 after TMZ administration." (PMID 37175410, 2023). "Some of the ADAMs, such as ADAM9, ADAM10, ADAM12, ADAM15, and ADAM17, are frequently upregulated in tumor tissues as well as cancer cell lines, and their expression often correlates with adverse patient survival and/or treatment response." (PMID 37495855, 2023). "To address this question, we performed mouse MC38 (ADAM17-positive CRC cells) tumor growth-inhibition studies with TMI-5 (Apratastat) in both WT and NOX1-deficient mice." (PMID 38137406, 2023).